RN7SL111P (RNA, 7SL, cytoplasmic 111, pseudogene)
Gene: Miscellaneous RNA gene on chromosome 2 (118,016,385 to 118,016,669, forward strand). Ensembl gene ENSG00000243510.
Homologues: Orthologues: chimpanzee Metazoa_SRP (99% identical), macaque Metazoa_SRP (89% identical). Paralogues in human: RN7SL1 (84% identical), RN7SL2 (84% identical), RN7SL3 (82% identical), RN7SL126P (82% identical), RN7SL45P (81% identical), RN7SL7P (81% identical), RN7SL655P (81% identical), RN7SL88P (81% identical), RN7SL122P (80% identical), RN7SL218P (80% identical), RN7SL326P (80% identical), RN7SL769P (80% identical), and 702 more.